PPARA (peroxisome proliferator activated receptor alpha)
Diseases named in the same sentence as PPARA in open-access papers (continued):
Sharing a sentence is not in itself a finding about the gene and the disease.
Hepatic steatosis (continued). "Lipogenesis is promoted by the downregulation of PPARα expression in hepatic steatosis, as reported." (PMID 39872862, 2024). "The upregulation of PPARα was interpreted as the fish's response to counteract the effects of liver steatosis." (PMID 38644412, 2024). "PPARα, a key regulator of lipid metabolism and mitochondrial function in the liver, can have beneficial effects on fatty liver disease." (PMID 39451567, 2024). "By enhancing fatty acid oxidation, PPARα activation aids in reducing TG and lipid droplet accumulation in hepatocytes, thereby mitigating fatty liver disease." (PMID 39451567, 2024). "Investigations into key enzymes and regulators, such as HMGCS2, BDH1, PPARα, and mTORC1, highlight the intricate interplay between ketone body metabolism and fatty liver disease." (PMID 39403635, 2024). "For example, PPARα knockout mice, which exhibit impaired ketogenesis with decreased ketogenic enzymes, Hmgcs2 and Bdh1, develop hepatic steatosis." (PMID 39403635, 2024). "Disruptions in key regulators of ketogenesis, including hormones such as insulin and glucagon and transcriptional regulators like PPARα and mTORC1, also contribute to the development of fatty liver disease." (PMID 39403635, 2024). "PPARα deficiency also abrogated the protective effects of herpetrione against NASH, suggesting that herpetrione protects against hepatic steatosis and inflammation by activation of PPARα signaling, thereby alleviating NASH." (PMID 38034083, 2023). "The SREBP-1c/PPARα ratio has also been reported to be a good marker for determining the rate of hepatic steatosis." (PMID 36937300, 2023). "MiR-155, which is induced in the liver of alcohol-fed mice, importantly contributes to hepatic steatosis by directly inhibiting PPARα expression." (PMID 38067261, 2023). "A previous study showed PRMT5 promoted the development of hepatic steatosis under a high-fat diet by facilitating the suppression of transcription regulators in mitochondrial biogenesis such as PPARα." (PMID 37834101, 2023). "In contrast, the ACVR1C gene is linked to “hepatic steatosis”, “glucose metabolism disorder”, and the canonical pathway’s “TGF-b signaling”, “WNT/b-catenin signaling”, and “PPARa/RXRa activation pathway”." (PMID 37511368, 2023). "The gene-specific deletion of PPARα promotes NAFLD, whereas the expression of PPARα and the use of PPARα agonists, such as fenofibrate, prevent hepatic steatosis, inflammation, oxidative stress, and liver injury in HFD-fed animals." (PMID 38004149, 2023). "Since fatty liver is a known causal risk factor for liver cancer, Ppara-null and PPARA-humanized mice are valuable models for examining the mechanisms of PPARα and age-dependent hepatocarcinogenesis." (PMID 37623879, 2023). "In the diet-induced fatty liver model of female rats, lipoic acid also improves the fatty liver by activating PPARα." (PMID 38089874, 2023). "Fenofibrate, a selective PPARα agonist, stimulates hepatic β-oxidation and reverses hepatic steatosis in high-cholesterol and fructose-enriched diet fed models." (PMID 36835279, 2023). "In conclusion, we determined CMA activity in the aged liver and discovered that CMA inhibition and NCoR1-mediated PPARα inactivation are responsible for aging-related fatty liver." (PMID 37524243, 2023). "A high-fat diet can reduce the expressions of PPARα, Cpt1α, and Acox1 genes in the liver of model group mice, indicating that the lipid oxidative metabolism pathway of non-alcoholic fatty liver mice was blocked by a high-fat diet." (PMID 37299470, 2023). "In a high-fat diet-induced mouse model of fatty liver disease, the release of interleukin-1 beta (IL-1β) by KCs promotes hepatic steatosis by inhibiting peroxisome proliferator-activated receptor alpha (PPARα) activity in hepatocytes." (PMID 38147020, 2023). "Saikosaponin d has been confirmed to alleviate high-fat-diet-induced hepatic steatosis in hybrid grouper by targeting the AMPK/PPARα pathway." (PMID 37760294, 2023).
Hepatic steatosis (continued). "Hepatocyte-specific knockdown of PPARα leads to hepatic steatosis by impairing hepatic and whole-body fatty acid homeostasis and increasing hepatic and plasma triglyceride, free fatty acid, and cholesterol levels." (PMID 36835279, 2023). "The administration of the plasmalogen precursor, AGs, prevents hepatic steatosis and non-alcoholic steatohepatitis by activating fatty acid oxidation through PPARα." (PMID 37367676, 2023). "As we predicted, high doses of icariin up regulated the expression of CPT1α, ACOX1, MCAD, and LCAD, key regulatory proteins of downstream fatty acid oxidation, by promoting the transcription of PPARα, which further alleviated hepatic steatosis in rats." (PMID 36677577, 2023). "For example, FTO expression is increased in NAFLD, and it promotes hepatic steatosis by targeting PPARα." (PMID 37334291, 2023). "Similar to our findings, restoring Nrf2 in MCD mice alleviated the hepatic phenotype toward a reduction in hepatic steatosis, mainly by activating PPARα and suppressing SREBP1." (PMID 36986192, 2023). "LAMP2A knockdown in the mouse liver resulted in hepatic steatosis, demonstrating that the NCoR1/PPARα pathway inhibited fatty acid oxidation." (PMID 37524243, 2023). "Through its interaction with adiponectin receptor protein 1 and 2, adiponectin activates AMP-activated protein kinase and induces peroxisome proliferator-activated receptor alpha (PPARα), thereby promoting fatty acid oxidation and reducing hepatic steatosis." (PMID 37868954, 2023). "Among them, PPARα regulates lipid metabolism in the liver and is related to hepatic steatosis, steatohepatitis, steatofibrosis, and liver cancer." (PMID 37886973, 2023). "Perturbation in Pparα expression, a crucial regulator of hepatic metabolism, is involved in the pathogenesis of various liver conditions such as hepatic steatosis, steatohepatitis, fibrosis, and hepatocarcinogenesis." (PMID 38068770, 2023). "We also found PPARα knockdown in the liver recapitulated B2D effects on glucose excursion and fatty liver disease in mice." (PMID 37417957, 2023). "Continuous activation of PPARα induces liver steatosis by increasing liver triglyceride synthesis, thus accelerating the development of HCC in patients with HCV infection." (PMID 37987033, 2023). "These outcomes indicate that PPARα-dependent lipophagy is involved in hepatic steatosis in the db/db mouse model and that SS, a PPARα agonist, represents a new therapeutic option for managing associated diseases." (PMID 36552704, 2022). "Dietary supplementation with NDGA ameliorated dyslipidemia and hepatic steatosis in ob/ob mice via PPARα-dependent and PPARα-independent lipid pathways and AMPK signaling." (PMID 35682715, 2022). "PPARα is a key regulator of fatty acid oxidation, and downregulation of PPARα contributes to hepatic steatosis and NAFLD." (PMID 35282837, 2022). "By enriching the KEGG pathway and analyzing the interactions between the 13 differential genes proteins using PPI, it was tentatively concluded that LZG improved liver steatosis in mice, mainly through the PPARα pathway." (PMID 35035496, 2022). "PPARα participates in fatty acid oxidation by regulating the transcription of fatty acid oxidation-related genes to reverse hepatic steatosis." (PMID 35347118, 2022). "Overall, FTO expression is increased in NAFLD, and it promotes hepatic steatosis by targeting PPARα." (PMID 35282837, 2022). "Lentinan can improve NAFLD by activating the peroxisome proliferator-activated receptor alpha (PPAR-α) pathway to improve hepatic steatosis and reduce oxidative stress and apoptosis." (PMID 36233011, 2022). "In rodents, the binding of miR-34a and PPARα hinders lipid metabolism and promotes hepatic steatosis, but circRNA_0046366 and circRNA_0046367 can compete with PPARα to bind miR-34a." (PMID 35595755, 2022). "In summary, FTO is upregulated in NAFLD and suppresses the expression of PPARα in hepatocytes, leading to hepatic steatosis." (PMID 35282837, 2022).
Hepatic steatosis (continued). "Of note, it has also been reported that the activation of the Keap1/Nrf2 signaling pathway to maintain a redox status mediates lipid metabolism-related genes (SREBP-1c and PPARα) to reduce hepatic steatosis in an HFD-induced obese animal model." (PMID 36358563, 2022). "It is noteworthy that PPARα activation improves inflammation, fibrosis, and hepatic steatosis in MAFLD model mice." (PMID 36164476, 2022). "Based on the in silico results, the effects of SSC on AMPK and PPARα activation and anti-hepatic steatosis in HepG2 cells were investigated." (PMID 35628280, 2022). "A unique epigenetic mechanism behind hepatic steatosis and accompanying oxidative stress is represented by the circRNA_0046367/miR-34a/PPARα regulatory system." (PMID 36552725, 2022). "Thus, PPARα may work to prevent the development of fatty liver caused by excessive sucrose intake." (PMID 36140300, 2022). "Previous studies have shown that PPARα knockout mice exhibit severe hepatic steatosis accompanied by a decrease in fatty acid uptake and oxidation." (PMID 35364708, 2022). "Bilirubin can also impact hepatic steatosis by acting as an activator of the nuclear hormone receptor PPARα." (PMID 36148775, 2022). "A recent study demonstrated that catalpol attenuated hepatic steatosis by activating PPARα-mediated fatty acid β-oxidation." (PMID 35628280, 2022). "Previous studies have proven fenofibrate (a PPARα agonist) treatment reverses ethanol-induced liver steatosis by stimulating the β-oxidation pathway." (PMID 35620283, 2022). "Wy14643 is another typical agonist of PPARα reversing insulin resistance and hepatic steatosis, although it also has the disadvantage of fibrates." (PMID 36589809, 2022). "Fibrates, which target PPARα, are prescribed clinically to lower serum lipids and also have beneficial effects on hepatic steatosis in animal models." (PMID 36148775, 2022). "For example, in a hepatocyte-specific PPARα knockout mouse model, impaired hepatic and systemic fatty acid homeostasis has been observed, leading to hepatic steatosis during aging." (PMID 35743814, 2022). "In mice models with PPARα gene deletion, hepatic steatosis is a characteristic trait in fasting or in fat-rich diets, confirming the involvement of PPARα in these processes." (PMID 35625520, 2022). "An FF-induced increase in Lpl expression in HHTg rats suggests that the beneficial effects of FF on circulating lipids and hepatic steatosis can be mediated by PPARα-activated LPL." (PMID 35678658, 2022). "In contradiction to its expression being reduced during steatogenesis, normalization of circRNA_0046367 eliminates miR-34a-induced PPARα inhibition and hepatic steatosis." (PMID 36552725, 2022). "Here, we used the TNFR1−/− deficient mice to determine its role in the general mechanisms of fatty liver disease in the genetically obese PPARα−/− mice." (PMID 36865784, 2022). "PPARα agonists, such as fenofibrate and bezafibrate, are widely used to treat dyslipidemia, preventing hepatic steatosis and improving insulin sensitivity." (PMID 34539442, 2021). "Oxidation of fatty acid and expression of fatty acid transport protein shares a close relationship with nuclear receptor PPARα and PPARγ in liver steatosis." (PMID 33935766, 2021). "Rodent models have consistently demonstrated the role of PPARα in fatty acid transport and beta-oxidation, leading to improvement in serum lipid profiles, hepatic steatosis, and insulin resistance." (PMID 34298687, 2021). "Given this, these results indicated that bixin upregulates Nrf2 signals and PPARα involved in HFD-induced hepatic steatosis." (PMID 33603948, 2021). "Deletion of PPARα decreased hepatic fatty acid β-oxidation and aggravated hepatic steatosis in mice." (PMID 34512784, 2021). "It has been shown that the activation of PPARα improves steatosis, inflammation, and fibrosis in rodent models of non-alcoholic fatty liver by promoting peroxisomal and mitochondrial β-oxidation." (PMID 35082691, 2021).
Hepatic steatosis (continued). "In fact, treatment of ArKO male mice with the PPARα agonist bezafibrate greatly limits hepatic steatosis." (PMID 34572151, 2021). "Studies have shown that PPARα agonists can significantly reduce blood lipid and fatty liver in rodents, and PPARα agonists also have stable hypolipidemic effects in human clinical diseases." (PMID 34681767, 2021). "By contrast to Ppara-/- mice, which exhibit mild hepatic steatosis, Acox1 null mice develop strong hepatic steatosis, showing a hepatic peroxisome proliferation and the sustained activation of PPARα and expression of its target genes." (PMID 34445672, 2021). "The ability of PPARα activation to improve liver steatosis and steatohepatitis as well as insulin resistance in rodents led to a few small clinical studies to determine the effects of fibrates on NAFLD progression." (PMID 34298687, 2021). "We thereby propose a unique “NR crosstalk” of PPARα-REV-ERBα in the regulation of the circadian clock gene program in the CLA-induced hepatic steatosis." (PMID 34722605, 2021). "Meanwhile, YCHT increases the expression of the PPARα gene, thus promoting lipolysis in the liver and finally improving the alcohol-induced hepatic steatosis in mice." (PMID 35003311, 2021). "PPARα−/− mice and hepatocyte-specific PPARα−/− mice exhibited malfunction in lipid metabolism during aging, which subsequently led to early hepatic steatosis." (PMID 34639224, 2021). "Based on our in vivo and in vitro results, AO markedly stimulated lipid consumption and attenuated liver steatosis accompanied by the activation of PPARα and ACOX1." (PMID 35087411, 2021). "PPARα-knockout mice showed impaired fatty acid oxidation and a lower metabolic rate, resulting in hepatic steatosis, while the rate of VLDL secretion and gluconeogenesis remained unchanged." (PMID 34745420, 2021). "In conclusion, chronic feeding of BE to STZ/HFD-induced T2DM in rats prevents hepatic steatosis and liver damage by its hypoglycemic and insulin-sensitizing effects and its ability to upregulate antioxidants and PPARα." (PMID 34943221, 2021). "Pioglitazone is classified as a weak ligand for PPARα, and as such reduces insulin resistance, suppresses inflammation, and infers a role in increasing β-oxidation; whilst improving hepatic steatosis and non-alcoholic fatty liver disease." (PMID 33983968, 2021). "Both circRNAs prevent the binding of miR-34a to PPARA and alleviate hepatic steatosis by restoring the lipid metabolism pathways and genes." (PMID 35052690, 2021). "Liver-specific Bvra−/− was found to have reduced Pparα activity and increased plasma glucose and insulin levels, with increased hepatic steatosis." (PMID 34943131, 2021). "For example, depletion of n-3 long polyunsaturated fatty acids decreased PPARα signals, contributing liver steatosis by inhibiting FFA oxidation." (PMID 33603948, 2021). "In an HFD-induced murine fatty liver disease, IL-1β released from KCs promotes hepatic steatosis by inhibiting PPARα activity in hepatocytes." (PMID 34956171, 2021). "It is well-described that in fatty liver disease there is an increase in hepatic lipid accumulation together with an increase in PPARa activity, as well as an upregulation of gluconeogenic, beta-oxidative, and ketogenic gene expression." (PMID 33919415, 2021). "In the present study, the EAf2 fraction ameliorated IR combined with fatty liver by enhancing the expression of GLUT2 and PPARα, thereby reducing intracellular lipid accumulation and ameliorating fatty liver." (PMID 34257694, 2021). "The role of hepatocyte PPARα for hepatic steatosis and liver-adipose axis was also intensively evaluated." (PMID 32192216, 2020). "To fully uncover the molecular mechanism by which RAGE regulates hepatic steatosis, we showed that PPARα expression was negatively regulated by RAGE." (PMID 32936538, 2020).
Hepatic steatosis (continued). "CP775146, a new selective PPARα agonist, significantly reduces the levels of serum TG and liver enzymes, improves hepatic steatosis induced by HFD, and decreases adipocyte droplet sizes." (PMID 32455134, 2020). "As previously discussed, NIK induction of liver steatosis was observed through regulation of PPARα phosphorylation and recruitment of ERK1/2 and MEK1/2." (PMID 33187137, 2020). "Based on our current data and previous studies clearly demonstrating the induction of PPARα by bilirubin and bilirubin nanoparticles, it is likely that the effects on hepatic steatosis are at least in part mediated via PPARα regulated mechanisms." (PMID 33390979, 2020). "The deletion of Bcl6 in the liver leads to a derepression of PPARα-driven enzymes mediating fatty acid oxidation and thus protects against high-fat diet-induced hepatic steatosis." (PMID 33117357, 2020). "It has been reported that during prolonged leucine deprivation resulting in severe liver steatosis, lipid synthesis was upregulated in the livers of Gcn2-/- mice due to failure to up-regulate peroxisome proliferator-activated receptor alpha (PPARα) expression." (PMID 33291840, 2020). "Consistent with that finding, pharmacological inhibition of NIK with B022 attenuated ethanol-induced hepatic steatosis and suppression of PPARα and fatty acid oxidation." (PMID 33187137, 2020). "Not surprisingly, mice with a hepatocyte-specific deletion of PPARα develop hepatic steatosis and NAFLD that is worsened on a high-fat diet." (PMID 33390979, 2020). "More recently, hepatic TFEB overexpression has been shown to induce the PGC1α/PPARα pathway to promote fatty acid oxidation and prevent chronic high-fat diet-induced hepatic steatosis in mice." (PMID 32681035, 2020). "The involvement of PPARα in GLP-1 mediated amelioration of hepatic steatosis, oxidative stress and liver injury was investigated in vivo and in vitro." (PMID 33746742, 2020). "Reduction of PPARα expression in the liver of patients with fatty livers has been reported; PPARα agonists, such as resveratrol, naringenin, trans-caryophyllene, and quercetin, are known to improve fatty liver disease and nonalcoholic fatty liver disease." (PMID 32630596, 2020). "PPARα-null mice exhibit phenotypes such as severe fatty liver and steatohepatitis and patients with NASH show a reduced expression of liver PPARα." (PMID 31974794, 2020). "The PPARα agonist can provide relief from insulin resistance and hepatic steatosis in high-fat-diet-fed mice." (PMID 32796820, 2020). "Some studies suggested that long-term activation of PPARα induced hepatocellular carcinoma in mice and was essential for the development of hepatic steatosis." (PMID 33029111, 2020). "Conversely to the GPS2 knockouts, hepatic deletion of TBL1 promotes hypertriglyceridemia and hepatic steatosis on both a normal chow or high-fat diet by impairing PPARα-driven lipid catabolism." (PMID 33117357, 2020). "Because AMPK and AKT phosphorylation and the levels of PPARα have been related to hepatic steatosis, Western blot analysis was carried out with liver samples of WT and TNAP haplodeficient mice fed the MCD or the control diet." (PMID 33374541, 2020). "It is known that errors in nuclear receptor signaling, including peroxisome proliferator-activated receptor alpha (PPARα), are involved in the pathogenesis of fatty liver disease." (PMID 32429274, 2020). "Corroborating our findings in fatty liver disease models, very different gene regulation by PPARα activation in human and mouse hepatocytes was observed, with more than 1800 inconsistently regulated genes, and only 204 commonly regulated genes." (PMID 33266321, 2020). "As a result of loss of PPARα repression, Gps2 LKO mice showed alleviated liver steatosis upon HFD feeding and improved fibrosis upon MCD feeding, due to increased lipid burning as detected by elevated ketone body levels." (PMID 30975991, 2019).